IL1A (interleukin 1 alpha)
Diseases named in the same sentence as IL1A in open-access papers (continued):
Sharing a sentence is not in itself a finding about the gene and the disease.
tumor (continued). "While the secreted form of IL-1α is highly pro-inflammatory in the TME and involved in tumor growth and invasiveness, its membrane form promotes anti-tumor immunity, and induces a reduction of tumor growth and invasiveness." (PMID 33806300, 2021). "We then tested whether hypoxia-induced IL1A and IL6 expression in tumor cells and macrophages when co-cultured together." (PMID 34362882, 2021). "In summary (graphical abstract), we reveal that SPTBN1 functions as a tumor suppressor to stabilize SOCS1 protein, controlling the cellular level of p65 to suppress the expression of inflammatory cytokines, IL-1α, IL-1β and IL-6, and the expansion of MDSCs and Foxp3+Treg cells." (PMID 33754058, 2021). "In this sense, we also acknowledge that potential dysregulation of inflammation-related genes included in our proposed molecular signature (e.g., IL1A, MCM2, MMP1, MMP12, and VEGFA) might be due to the inflammation favoring tumor maintenance and progression." (PMID 34638231, 2021). "IL-1α and IL-1β are both constitutively expressed in OSCC, can be found in the saliva of patients with OSCC, and have been reported to have important functions in OSCC carcinogenesis and tumor progression." (PMID 35047997, 2021). "A small subset of BC cells specifically expressing CXCR3 exhibited tumor-initiating ability when cotransplanted with fibroblasts, driving JNK signaling, increasing expression of IL-1α/β, forming a supportive metastatic niche, and promoting lung metastatic tumor growth." (PMID 34602858, 2021). "Taken together with our findings, these data suggest that the transcriptional activation of both IL1A and IL1B may be functionally relevant within the tumor microenvironment of squamous-subtype PDA tumors." (PMID 32329713, 2020). "Instead, we found that IL-1α was significantly increased in the tumor tissues than non-cancerous tissues." (PMID 33187551, 2020). "Many studies have reported that a series of proangiogenic cytokines are enriched in tumor-derived EVs, such as VEGF, fibroblast growth factor (FGF), interleukin (IL)-6, IL-1α, and tumor necrosis factor alpha (TNF-α), which directly contribute to tumor angiogenesis." (PMID 33628730, 2020). "Indeed, the neutralization of IL-1α in NMU-treated mice significantly reduced the levels of tumor areas than control group and, very importantly, NSCLC patients who presented high levels of IL-1α and caspase-4 had lower median survival rate." (PMID 33187551, 2020). "Although IL1A plays different and sometimes opposite roles when expressed by cells of the tumor microenvironment, when it is expressed by CRC cells, it is immunostimulatory and induces an anti-tumor immune response." (PMID 32290493, 2020). "Others have described modulation of cytokine production of IL-1α, IL-1β, IL-2, IL-4, IL-6, IL-8, IL-10, IL-17A, TNF-α, and IFN-γ on tumor cells treated with conventional PDT, but their increase or decrease seems to highly depend on the cell line and PDT protocol used." (PMID 32326519, 2020). "CCL3, CCL4, IL-1α and IL-12/IL23p40 were highest in individuals with no adverse features of tumor biology, whereas levels of Tie2 and VEGF were lowest in this cohort." (PMID 33202734, 2020). "Therefore, IL-1α signaling is a potential therapeutic target against PDAC cells and inflammatory CAFs in the tumor microenvironment." (PMID 32546182, 2020). "Tumor-specific effector TH1 cells establish a pro-inflammatory tumor microenvironment after tumor infiltration and their ability to mediate anti-cancer immune responses depends on IL-1 signaling, which can be delivered by both IL-1α and IL-1β." (PMID 33584721, 2020). "In addition, the cytokines IL-1α, IL-1β, IL-6, IL-17A, and TNF-α promote tumor initiation, progression, angiogenesis, and metastasis in many human malignancies, including CRC, and our findings are consistent with previous studies." (PMID 33488574, 2020).
tumor (continued). "Both IL‐1α and IL‐1β are able to increase secretion of SASP factors such as IL‐6 and IL‐8, which have known oncogenic properties, and IL‐1α inactivation in senescent cells impairs tumour progression." (PMID 33095981, 2020). "We also found a significant interaction (p=0.02) between the 2/1 IL-1α profile score and EGFR+ expression suggesting that this particular 2/1/EGFR+ expression profile could be considered a predictor of tumor recurrence." (PMID 31320902, 2019). "d Tumor cell- and TAM-derived IL-1α and IL-1β, respectively, induce TSLP secretion by CAFs." (PMID 30760333, 2019). "Breast tumor-derived IL-1α, acting on tumor-infiltrating myeloid cells, induced the expression of thymic stromal lymphopoietin (TSLP), which was not only a critical tumor survival factor, but is also required for the metastatic spread of the tumor cells." (PMID 31231372, 2019). "Nevertheless, in vivo, we show remarkable tumor regression in 8 of 9 mice with a single administration of IL-1α-NPs in combination with cetuximab with no obvious signs of toxicity compared to the dramatic weight loss seen with soluble rIL-1α." (PMID 30890189, 2019). "IL-1 signaling blockade did not affect the anti-tumor efficacy of cetuximab, while increased IL-1α expression using polyanhydride nanoparticles in combination with cetuximab safely and effectively induced a T cell-dependent anti-tumor immune response." (PMID 30890189, 2019). "This phenotype was shown to be IL-1α dependant, indicating that IL-1α-IL1R signaling may be tumor-suppressive in PyMT-driven breast cancer." (PMID 31231372, 2019). "Tumor growth and neovascularisation is significantly decreased when BMP-6 is expressed in IL-1α knockout (KO) mice compared to wild type controls; indicating that IL-1α is mediating angiogenesis in this context." (PMID 31293586, 2019). "We identified the CT tumor anatomic region as harboring the majority of genes significantly differentially expressed between the two neurologic deficits groups, with IL1A (interleukin 1 alpha) and IL1B (interleukin 1 beta) as putative regulators of their expression profile changes." (PMID 31231419, 2019). "IL1A and IL1B were found to be significantly increased in tumors (b p < 0.0001 and p = 0.003, respectively) compared to normal samples while IL1RN (IL-1RA) was significantly decreased in tumor versus normal tumors (p = 0.02)." (PMID 31346466, 2019). "Ongoing studies in our group are exploring whether α3β1 on tumor cells influences CAF differentiation or function within the TME, through the secretion of IL-1α or other paracrine factors." (PMID 31137641, 2019). "Acid-induced NF-κB activation downstream promotes the secretion of several cytokines, chemokines, and growth factors (IL1a, IL1b, IL6, IL8, IL23a, CCL5, CCL7, CXCL2, GM-CSF, and G-CSF) that can elicit local cancer aggressiveness, tumor immune escape, and tumor-induced nociception and hyperalgesia." (PMID 30825056, 2019). "Moreover, the IL-1α gene has been reported to be regulated by sp1 suggesting a feed-forward relationship between IL-1α and sp1 which would ultimately promote EGFR signaling and tumor progression." (PMID 31320902, 2019). "Of note, IL-1α–engineered tumor cells rarely develop into tumors, and if they do, the tumors are quickly destroyed through a mechanism that involves CD8+ T cells and natural killer cells, and IL-1α enhances immunoediting in the tumor microenvironment." (PMID 31406955, 2019). "The cytokine profile identified in the ACP RNA-Seq dataset, in particular the significantly higher expression of IL1A (18.1-fold), IL18 (14.8-fold), TNF (10.4-fold) and IL1B (7-fold) in human ACP tumours relative to controls, was suggestive of inflammasome activation [Suppl." (PMID 29541918, 2018). "High primary tumour burden was found in both IL-1R1 −/− and IL-1A −/− mice, and this phenotype was independent of caspase-1/-11." (PMID 29760166, 2018).
tumor (continued). "As we have already identified IL1α, IL1β and GCLM as important transcriptional targets of glucose-induced H3 ubiquitination, we investigated whether they are involved in tumour sphere formation." (PMID 28300060, 2017). "Interestingly, number of EMT/CSC-related factors such as IL1a, IL6, NOS2 and TGFb129, 35, 36, were highly expressed in BM or tumour-derived mMDSCs and also further enhanced the expression of these genes in tumour cells upon co-culture." (PMID 28382931, 2017). "Numerous studies have demonstrated that RT leads to increased local production of soluble factors that promote anti-tumor immunity by enhancing activation of local innate immune cells and recruitment of tumor-reactive T cells (e.g., CXCL16, IL-1α/β, IFNγ, and TNFα)." (PMID 28134800, 2017). "IL-1α protein levels at the treatment sites were high prior to treatment, with IL-1α expression restricted to skin rather than the B16 tumour." (PMID 27100888, 2016). "In particular, the activation of NLRP3 inflammasome via TLR4 signalling led to IL-1β release after caspase-1 activation, whereas, the activation of caspase-11 was important for both IL-1α release and NLRP3-dependent IL-1β release in the lung of tumor-bearing mice." (PMID 27528423, 2016). "Microenvironment-derived IL-1β, rather than IL-1α, was found to be required for invasiveness and angiogenesis in different tumor cells." (PMID 24901233, 2014). "Further analysis revealed a unique transcriptional profile in tumor cells that arise in the absence of IL-15 that included a significant increase in the expression of IL-1α and IL-1α-regulated cytokines." (PMID 24416335, 2014). "The novelty of our study is that the combination of ALT-803 plus BCG stimulated the production of key sera and urinary cytokines (e.g., IL-1α, IL-1β and RANTES) leading to the activation and proliferation of NK cells, which led to the significant reduction in tumor burden." (PMID 24896845, 2014). "Therefore WP1066 inhibition of STAT3 activity and tumour progression was due in part to reduced polymophonuclear infiltration and reduced STAT3-dependent transcription of pro-inflammatory IL-6, IL-11, IL-1α, IL-1β and COX2 genes." (PMID 24804649, 2014). "In addition to the autocrine effects of IL-1α on tumor cell migration, the protein also acts in a paracrine manner by promoting a CAF phenotype supporting the tumor cell migration." (PMID 23951028, 2013). "The p38MAPK signaling in tumor cells were shown to be involved in the upregulation of inflammation in CAFs via the induction of IL-1α and to our knowledge has this not been shown previously." (PMID 23951028, 2013). "In contrast, the signaling events leading up to the expression of IL-1α by tumor cells are not well elucidated." (PMID 23951028, 2013). "In contrast, until very recently the signaling events leading up to the expression of IL-1α by the tumor cells had not been elucidated." (PMID 23951028, 2013). "Some of these gene nodes have been shown to be functionally involved in other cancer types, including regulation of tumor cell proliferation (Creb, C/ebp, ATF3, ATF4), invasion (MTHFD2, FGF2) and metastasis (PTGS1/COX1, E-selectin, ATF3, FGF2, IL1A, MMP1, MMP13)." (PMID 24124450, 2013). "The IL1 isoforms, IL1A and IL1B, have previously been described as both anti-invasive and pro-invasive, suggesting no clear indication of their role in cancer progression; however, our findings report a new protective function for IL1B in tumour invasion." (PMID 23867201, 2013). "In the tumor milieu, extracellular levels of IL-1α are usually low and do not stimulate broad inflammation that promotes progression." (PMID 23847618, 2013). "Not all patients responded to anti-IL-1α treatment, which raises the issue of the control of intracellular IL-1α activity in tumor cells." (PMID 24312098, 2013).
tumor (continued). "However, K14.IL-1α transgenic mice are completely resistant to skin tumorigenesis induced by DMBA/TPA or by overexpression of activated H-ras (Tg.AC transgenic mice), perhaps due to IL-1α activation of the innate immune system to eliminate initiated cells." (PMID 21297902, 2010). "The results showed that hBD-3 induced the expression of IL-1α, IL-6, IL-8, and CCL18, suggesting that hBD-3 may activate macrophages and stimulate their tumor-promoting capacity." (PMID 20544025, 2010). "The tumor tissue stained positive brown, whereas the normal tissues were negative for IL-1α." (PMID 40940885, 2025). "Moreover, functional studies are necessary to investigate whether inhibiting IL-1α, IL-12, or TGF-β1 can reduce tumour cell growth, migration, or invasion in vitro, and to examine their role in tumour progression in animal models." (PMID 41465261, 2025). "This heterogeneity may be influenced by tumor subtype; for example, basaloid OSCC—characterized by higher invasiveness and epithelial–mesenchymal transition (EMT) potential —showed a tendency toward stronger IL-1α immunoreactivity." (PMID 40940885, 2025). "In NOD.SCID mice, both types of cells, with and without IL-1α, induced rapid tumor growth." (PMID 38612760, 2024). "It is worth noting that the depletion of IL-1β during tumor cell pyroptosis significantly attenuates antitumor immunity, suggesting that IL-1α may not play a major role in inducing antitumor immunity." (PMID 38391959, 2024). "There were no evident differences in tumor growth between the two groups up to approximately day 14; nevertheless, even at these early time intervals, increased recruitment of immune cells into 4T1 IL-1α KO tumors was observed." (PMID 38612760, 2024). "Interestingly, the strongly augmented IL-1 receptor signaling observed in IL-1Ra KO mice did not significantly affect 4T1/WT tumor development in these animals, suggesting the dominant effect of intracellular IL-1α, independently of IL-1 receptor activation." (PMID 38612760, 2024). "Thus, both tumor- and the TME-derived IL-1α contribute to the progression of TNBC in mice." (PMID 38612760, 2024). "Notably, IL-1A is an effective activator of anti-tumor cytotoxic lymphocytes (such as NK cells and CD8+ cells), and IL-1A derived from necrotic cells may mainly serve as a warning for promoting carcinogenic inflammation." (PMID 39461030, 2024). "We found that IL‐1α treatment whether in free form or encapsulated all exhibited similar tumor growth inhibition compared to Blank‐MPs and saline controls, suggesting that the use of CPH:SA MPs did not significantly suppress the anti‐tumor effects of IL‐1α." (PMID 37206237, 2023). "Additionally, encapsulation of IL‐1α into CPH:SA MPs did not reduce the bioactivity of IL‐1α nor the in vivo anti‐tumor immune response which are all promising indicators for further study as an acceptable cancer immunotherapeutic strategy." (PMID 37206237, 2023). "Nevertheless, these data suggest that the use of CPH:SA MPs did not significantly suppress the anti‐tumor effects of IL‐1α and that further manipulation of the MP dose and dosing schedule may yield significant and durable anti‐tumor effects." (PMID 37206237, 2023). "On the other hand, in OSCC, tumor progression and metastasis are also sustained by the presence of hypoxia-inducible factor (HIF) and related genes induced by hypoxia, such as VEGF, interleukin 1A (IL-1A), endothelin 1, platelet-derived growth factor B (PDGFB) and erythropoietin (EPO)." (PMID 35890188, 2022). "Our results demonstrated that the mRNA expressions of IL-5, IL-1A, CXCL10, TNFSF4 and INHBE were significantly altered when regulating C1QTNF6, which suggested the essential implications of the cytokine-cytokine receptor interaction pathway in the process of C1QTNF6 regulating tumor progression." (PMID 35879698, 2022).
tumor (continued). "Moreover, with or without supplementation of IL-1α, tumor-induced osteoclastogenesis was sensitive to CBD and resistant to denosumab, whereas RANKL-induced osteoclastogenesis was resistant to CBD and sensitive to denosumab." (PMID 36614130, 2022). "In addition, there is a significantly higher incidence of liver recurrence in patients with tumors expressing IL-1α compared to those without, hence, again showing a correlation between IL-1α expression in tumor and metastasis." (PMID 33430381, 2021). "Interestingly, we observed that although the serum levels of several cytokines including IL‐6, TNF‐α, and IL‐1β (but not IL‐1α) increased in C26‐tumor‐bearing mice, these effects were prevented by treatment with GW (Fig EV3, EV4D–G)." (PMID 34096686, 2021). "IL-1 is an immunosuppressive cytokine with two different isoforms, IL-1α and IL-1β, which is mainly produced by tumor cells and immune regulatory cells through autocrine or paracrine in the TME and plays an important role in promoting tumor occurrence and development." (PMID 34625124, 2021). "VEGF-A and IL-1α were higher in CSF of patients with anti-NMDARE but no tumor compared to those with paraneoplastic anti-NMDARE may suggest a different inflammation process." (PMID 32771066, 2020). "Moreover, the therapeutic response of two independent tumor models to treatment with doxorubicin diminishes upon treatment with an anti-IL-1β, but not an anti-IL-1α neutralizing antibody." (PMID 33584721, 2020). "The expression of TNF-α, IL-1α, and IL-6 from MDA-MB-231 cells was shown to be inhibited by apigenin, and the inhibition of TNF-α-induced CCL2 release by apigenin was thought to suppress tumor migration and metastasis through the regulation of tumor microenvironment." (PMID 31252615, 2019). "The IL-1α-expressing tumor cells were seen to predominantly not result in tumor development." (PMID 31231372, 2019). "Reduction of IL-1α expression did not affect tumor cell proliferation in vitro." (PMID 29502208, 2018). "However, levels of IL-1α, IL-4, IL-10, IL-13, and TNFα were not significantly altered by tumor growth." (PMID 26347589, 2015). "Moreover, the increased expression of IL-1α, IL-1β, VEGF-A, VEGF-C, and VEGF-D in tumor stromal cells, including macrophages, suggests a mechanism by which tumor growth, angiogenesis, lymphangiogenesis, and lymph node metastasis are enhanced in highly metastatic cancer cells." (PMID 24924428, 2014). "Thus, in mice deficient in IL-1β, almost no inflammatory response was observed during tumor development, lack of IL-1α did not impair inflammation as compared to WT mice, while an heightened inflammatory response was evident in IL-1Ra KO mice." (PMID 23847618, 2013). "The levels of GM-CSF, IL-1α, and IL-1β were not altered in the tumor following radiation therapy." (PMID 23936036, 2013). "Thus, fibrosarcoma cell-derived IL-1α and IL-1β do not act in concert and each IL-1 molecule has unique effects on tumor invasiveness or on anti-tumor cell immune responses." (PMID 23847618, 2013). "Our data demonstrates that while the level of GM-CSF, IL-1α and IL-1β per mg of tumor does not change following radiation therapy, the decrease in size of the tumor will result in fewer of these and other tumor-derived growth factors in the tumor-bearing mouse following radiation therapy." (PMID 23936036, 2013). "IL-1α was exclusively located in tumor cells while normal pancreatic tissue stained negative." (PMID 22190968, 2011). "Our findings highlight several important considerations, including (i) the role of IL-1α, which is not inhibited with canakinumab alone, and (ii) the role of timing (i.e., whether IL-1 inhibition is introduced during the early stages of tumor initiation versus once tumors are fully established)." (PMID 39236155, 2024). "However, neutralization of extracellular IL-1α could not recapitulate the strong tumor suppression induced by IL-1α KO." (PMID 38612760, 2024).